TNF (tumor necrosis factor)
Diseases named in the same sentence as TNF in open-access papers (continued):
Sharing a sentence is not in itself a finding about the gene and the disease.
endotoxemia (continued). "To study the kinetics of TNF release in endotoxemia following VNS, we subjected rats to vagus nerve stimulation (VNS) for 60 s at 10 Hz, or sham surgery." (PMID 30538698, 2018). "Consistent with those ideas, they found that electrical vagus stimulation elevated ACh concentrations in the spleen, and attenuated serum TNF-α levels during endotoxemia." (PMID 28932225, 2017). "Galantamine dramatically decreases circulating TNFα and IL-6 and improves survival in a murine endotoxemia model." (PMID 29163522, 2017). "Compared to PMB, which is a known LPS neutralizer, mutant peptide MC1-1 showed an enhanced ability to inhibit TNF-α and IL-6 production and to protect mice with endotoxemia from death at the same concentration." (PMID 28054660, 2017). "Pharmacological approaches to block TNF-α and NO production protected both the Ptpn6f/f and the Ptpn6H-KO mice against deadly LPS-mediated endotoxemia." (PMID 28533521, 2017). "Hemoadsorption therapy with a clinically approved device (CytoSorbTM) removes cytokines (interleukin-6, interleukin-10, and tumor necrosis factor, amongst others) and improves short-term survival in a rat model of endotoxemia." (PMID 28779451, 2017). "To determine if the protective activity of N4 was associated with inflammatory cytokines, we measured the concentrations of interleukin-6 (IL-6), IL-1β, and tumor necrosis factor alpha (TNF-α) in the sera from mice with endotoxemia." (PMID 27795369, 2017). "CGA-JK3 suppressed mRNA and protein levels of TNF-α or IL-1α in LPS-activated macrophages, which was consistent with the in vivo effects in endotoxemia- or ALF-induced mice." (PMID 28145460, 2017). "In a rat model of LPS-induced septic shock, electrical stimulation of the efferent vagus nerve protected animals from endotoxemia and attenuated the increase in serum and liver TNF-α levels." (PMID 28932225, 2017). "TNF‐α is the main cytokine synthesized during endotoxemia and is considered to be responsible for the expression of IL‐1β, IL‐2 and IL‐6." (PMID 28684640, 2017). "Borovikova reported that electrical stimulation of the peripheral vagal fibers limited TNF production in the liver of endotoxemia rats and vagotomy enhanced the inflammation and mortality of experimental animals." (PMID 28197102, 2017). "Adding to the complexity, administration of plerixafor in a model of LPS-induced endotoxemia resulted in enhanced serum levels of TNF, IFN-γ and NO levels and overall worsened outcomes." (PMID 29232699, 2017). "Splenic-denervation and catecholamine depletion abrogated the decrease in TNF level induced by activation of splenic sympathetic nerve in endotoxemia." (PMID 28197102, 2017). "In a mild model of endotoxemia (induced by an i.p. challenge with 10 mg/kg LPS), TNF and IL-12p40 concentrations in blood and mortality rates (83 vs 100%, P = 0.3) were comparable in SIRT2+/+ and SIRT2−/− mice." (PMID 28894448, 2017). "Up-regulated production of pro-inflammatory cytokines in the myocardium, such as tumor necrosis factor-α (TNF-α) and interleukin-1β (IL-1β) plays an important role in cardiac contractile depression during endotoxemia." (PMID 28152512, 2017). "Central injection of CNI-1493 during endotoxemia significantly reduced serum TNFα levels and this effect is mediated through the VN." (PMID 29163522, 2017). "In a severe model of endotoxemia (induced by 25 mg/kg LPS), TNF, IL-6, and IL-12p40 concentrations in blood and mortality rates (88% in both groups, P = 0.69) were strongly increased, but remained similar in SIRT2+/+ and SIRT2−/− mice." (PMID 28894448, 2017). "Body weight doses from 2.5–7.5 mg/kg of N2 and N6 enhanced the survival rate of peritonitis- and endotoxemia-induced mice; reduced the serum IL-6, IL-1β and TNF-α levels; and protected mice from lipopolysaccharide-induced lung injury." (PMID 28611436, 2017). "The use of corticosteroids and anti-TNF-α has been effective in animal models of endotoxemia, but has failed in clinical trials." (PMID 29061119, 2017).
endotoxemia (continued). "In these in vivo models of endotoxemia, the low-dose LPS challenge of horses resulted in a predictable effect on increasing plasma TNF-α activity that peaked between 1–4 h (average 1.5–2.5 h)." (PMID 27316332, 2016). "We then aimed to determine the liver cell population responsible for the production of the elevated TNF alpha serum levels observed in endotoxemia, particularly after co-treatment with AMD3100 and LPS." (PMID 27716214, 2016). "In accordance with previous investigations, which found that CXCR4 agonists reduce serum levels of pro-inflammatory cytokines in endotoxemia, we detected increased levels of serum TNF alpha and IFN gamma after CXCR4 blockade." (PMID 27716214, 2016). "As macrophages are major cytokine-producing cells, playing a key role in the response to endotoxemia, we also examined how the hormone affected LPS, IL-6 or TNFα signalling in these cells." (PMID 27484112, 2016). "In this study, the combination of Pep19-2.5 with ibuprofen caused a decrease of TNFα and PGE2 levels in the mouse model of endotoxemia." (PMID 26197109, 2015). "The fact that endotoxemia was primarily observed in patients with diarrhea who also showed more elevated TNFα concentrations, suggests that mucositis and altered microbial-host interactions are at the heart of pelvic radiation disease." (PMID 25955845, 2015). "To summarize, chronic low-grade endotoxemia, as seen in the case of T1DM, was associated with decreased levels of LBP and EndoCAb and with elevated levels of TNF-α, IL-6, IL-1β and GM-CSF, indicating chronic inflammation." (PMID 26367738, 2015). "The most frequently measured cytokines in studies of low-dose endotoxemia are the pro-inflammatory cytokines IL-6 and TNFα and the anti-inflammatory IL-1 receptor antagonist (IL-1ra)." (PMID 25893426, 2015). "Production of proinflammatory cytokines such as IL-1-β, IL-6, and TNF-α has recently been found in skeletal muscle tissue during special conditions such as endotoxemia." (PMID 25821631, 2015). "Another model of LPS-induced endotoxemia in rats also demonstrated reductions in myocardial contractility depression and in TNF-α levels after fenofibrate treatment." (PMID 25667670, 2015). "LPS induced TNF-α has been shown to be a major factor responsible for myocardial depression during endotoxemia and cardiomyocytes are the major local source of TNF-α." (PMID 26486084, 2015). "Following chronic alcohol exposure, rats developed endotoxemia, showed enhanced levels of liver enzyme markers, NF-κB levels, and increased cytokines such as TNF-α and IL12/p40 subunit, and reflected significant histological changes in the intestine and liver." (PMID 24966470, 2014). "Proinflammatory cytokines play a crucial role in endotoxin-induced liver injury leading to hepatotoxicity.TNF- α and IL-6 cytokine were found to be highly expressed in liver during inflammation as a result of endotoxemia." (PMID 25184525, 2014). "The preventive administration of fucoidan to mice with endotoxemia resulted in inhibition of increased levels of proinflammatory cytokines (TNFα and IL-6), as well as decreasing of the processes of hypercoagulability." (PMID 24492521, 2014). "Galantamine, an ACh esterase inhibitor, attenuates serum TNF-α and improves survival in murine endotoxemia." (PMID 24914105, 2014). "The key finding of the study is that acetate-buffered solutions induce a significant higher inflammatory response in the kidney, the liver and the lung as measured by expression of CINC-1 and TNFα in rats suffering from acute endotoxemia." (PMID 24709833, 2014). "Endotoxemia depresses cardiac function via upregulation of the expression of cardiodepressant cytokines, including TNF-α, IL-1β and IL-6." (PMID 25209241, 2014). "Stimulation of the vagus nerve decreases release of the proinflammatory cytokine TNFα in a model of endotoxemia and vagotomy increases serum levels of TNFα." (PMID 25105129, 2014).
endotoxemia (continued). "It is consistent with the report that the inhibition of Na/K-ATPase promoted myocardial TNF-α protein production and cardiac dysfunction during endotoxemia through activating Ca(2+)/CaMK/mTOR signaling." (PMID 25073093, 2014). "Recently, direct electrical stimulation of the peripheral VN in the liver of endotoxemia rats was found to inhibit TNF-a synthesis, attenuate peak serum TNF-a levels, and prevent the development of shock." (PMID 25036185, 2014). "We here leveraged the established model of human endotoxemia to examine the effect of TNFα inhibition on the genome-wide transcriptional responses in circulating leukocytes induced by intravenous LPS administration." (PMID 24236088, 2013). "High levels of TNF-α were found in serum and lung in rats with endotoxemia, and more albumin was present in endotoxemic lungs than in control ones." (PMID 23671873, 2013). "We here leveraged the established model of human endotoxemia to examine the effect of the TNFα antagonist, etanercept, on the genome-wide transcriptional responses in circulating leukocytes induced by intravenous LPS administration in male subjects." (PMID 24236088, 2013). "Investigation into the role of nutrient modulation of the cholinergic anti-inflammatory pathway has shown that ingestion of lipids attenuated TNFα serum levels in rodent models of hemorrhagic shock and endotoxemia." (PMID 24356325, 2013). "In this model, it is well-established that vagus-nerve stimulation during endotoxemia specifically attenuates TNF-α production by macrophages residing in the spleen." (PMID 23840379, 2013). "Increased levels of (TNF-α) in cirrhosis are secondary to endotoxemia as a result of bacterial translocation in these patients." (PMID 24102057, 2013). "These suggested that TNF-α signaling played a significant role on cardiac dysfunction in endotoxemia." (PMID 23659427, 2013). "We found higher TNF-α levels in serum and bronchoalveolar lavage fluid in diabetic rats during systemic endotoxemia." (PMID 23671873, 2013). "We further demonstrated that ATF3 gene knockout in mice subjected to LPS-induced endotoxemia correlates with an increase in the mortality rate and the elevated expression of IL-6, TNF-α, NO, MCP-1, and HMGB1 in the lung tissues or serum." (PMID 24062788, 2013). "ChE inhibitors galantamine and huperzine, reduced TNF-α in the serum and spleen and improved survival of mice with endotoxemia induced by injection of LPS." (PMID 23469045, 2013). "Although infection and endotoxemia are potent stimulants of TNFα production, the studies also found that intestinal ischemia–reperfusion increased TNFα levels in the serum and intestinal tissue of rat." (PMID 23626828, 2013). "Results of the present study are consistent with this proposed signaling pathway, whereby concomitant increases in Sphk-1, CD14 and TNF-α were identified in hepatic tissues of animals subjected to endotoxemia." (PMID 23817990, 2013). "Mice injected intraperitoneally with recombinant CD6 were protected from lethality due to endotoxemia and presented a reduction in serum TNFα abundance." (PMID 24236088, 2013). "Noncleavable transmembrane TNF transgenic mice were fully protected from endotoxic shock, pointing towards the importance of TNF cleavage in the endotoxemia model." (PMID 23723167, 2013). "TNF-α plays an important role in this endotoxin-induced shock because serum TNF-α level increases during lethal endotoxemia." (PMID 23671873, 2013). "Endotoxemia induced a characteristic cytokine response with high levels of key inflammatory cytokines, such as IL-1β, TNF-α and IL-6, but EP and GL significantly attenuated such responses compared with the con group." (PMID 23497622, 2013). "IL-10 is an anti-inflammatory cytokine that controls the endogenous production of TNF-α during endotoxemia and reduces LPS stimulation when added exogenously." (PMID 24385684, 2013).
endotoxemia (continued). "The combined chemical blockage of both CCK-R subtypes (CCK1-R, CCK2-R) in rodent models of endotoxemia and hemorrhagic shock abrogates the lipid induced inhibition of TNFα release into plasma." (PMID 24356325, 2013). "Endotoxemia led to a rise in body temperature and inflammatory symptom scores and a rise in plasma TNF-α, IL-6, IL-10 and IL-1RA." (PMID 24358337, 2013). "Myeloid-specific TAK1 deficiency in mice leads to increased levels of circulating IL-1β, TNF and reduced IL-10 after LPS challenge and sensitizes them to LPS-induced endotoxemia." (PMID 22348103, 2012). "The activation of macrophages by LPS is an important event during endotoxemia, LPS activates macrophages to produce cytokines such as TNF-α and IL-10." (PMID 23285207, 2012). "In these studies, the reduced release of cytokines such as TNF-α, IL-1β, and IL-10 was quite dramatic in an endotoxemia model." (PMID 23109904, 2012). "Platelet-derived TLR-4 has been suggested to mediate various inflammatory responses in endotoxemia, including production of tumor necrosis factor alpha (TNF-α) and interleukin-1 beta (IL-1β), two cytokines reported to enhance microvascular thrombosis." (PMID 22911769, 2012). "The current study indicates that renal protection induced by T-5224 administration during endotoxemia occurs by controlling the expression of TNF-α and other downstream mediators." (PMID 23173923, 2012). "We pursued a role for TNF-α and IL-1β based on published data linking these pro-inflammatory cytokines to platelet-dependent responses in endotoxemia and their reported role as mediators of microvascular thrombosis." (PMID 22911769, 2012). "When human subjects adopted an acute exercise protocol (75% VO2max), however, the production of TNF-α elicited by low-grade endotoxemia was inhibited." (PMID 22989045, 2012). "Apart from the inhibition of serum TNF-α during endotoxemia, T-5224 decreased other serum cytokines, namely IL-1β and IL-6." (PMID 23173923, 2012). "Specifically, the role of TNF-α has been shown to be critical in the inflammatory response in endotoxemia-related AKI." (PMID 23173923, 2012). "In in vivo, endotoxemia induced by intraperitoneal injection of LPS (5 mg/kg BW), at 4 h after induction, serum level of TNF-α was significantly higher in MFG-E8−/− mice (837 pg/mL) than that of WT (570 pg/mL, P<0.05)." (PMID 22114683, 2011). "Recently developed novel cytokine antagonist therapies targeting TNF-α and IL-6 have been found to be quite effective in certain types of endotoxemia." (PMID 22114683, 2011). "To compensate the deficit of MFG-E8 that occurred during LPS-treatment, we administered rmMFG-E8 exogenously into the WT mice and examined its effects in TNF-α production during endotoxemia." (PMID 22114683, 2011). "Collectively, these evidences strongly supported the notion of MFG-E8-mediated downregulation of TNF-α production in endotoxemia." (PMID 22114683, 2011). "IL-13RA1 mediates translational repression of TNF-α mRNA in LPS-stimulated monocytes and is required for IL-13-mediated protection of mice from lethal endotoxemia." (PMID 20105294, 2010). "Exogenous administration of recombinant IL-10 protects mice from lethal endotoxemia by reducing TNF-α release." (PMID 19725984, 2009). "• Circulating Ang-2 appears in the systemic circulation during experimental human endotoxemia in a distinctive temporal sequence and correlates with TNF-alpha and E-selectin levels." (PMID 19416526, 2009). "To verify the crucial role of the α2A-AR in the proinflammatory response to NE in endotoxemia, we measured plasma levels of TNF-α after intraperitoneal injection of LPS (7.5 mg/kg) and systemic intravenous administration of NE." (PMID 19430535, 2009). "As previously shown, the release of TNF-alpha and several other cytokines during human endotoxemia is blocked by p38 MAP kinase inhibition in a dose-dependent manner." (PMID 19416526, 2009).
endotoxemia (continued). "It has been over two decades since TNF-α was identified as one of the major mediators of endotoxemia and cachexia." (PMID 19133137, 2009). "Unlike other pro-inflammatory cytokines, HMGB1 is a "late-appearing" inflammatory mediator, because its release during endotoxemia is delayed in comparison with the rapid increase of early pro-inflammatory cytokines such as IL-1β, IL-6 and TNF-α." (PMID 19799777, 2009). "High-dose prednisolone (10 mg/kg) administered orally 2 hours before LPS challenge was able to significantly reduce serum TNF-α in an acute model of rat endotoxemia." (PMID 19171052, 2009). "Monocytes/macrophages are known to express uPAR, and levels of expression are reported to be elevated during endotoxemia and by various cytokines including IL-1β, TNF-α, and TGFβ1." (PMID 19459212, 2009). "Previous studies have demonstrated a critical role for the pro-inflammatory cytokines IL-1β and TNF-α in disease pathogenesis during endotoxemia." (PMID 18706086, 2008). "Endotoxemia led to changes in inflammation and coagulation, including pulmonary neutrophil accumulation paralleled by increased TNFα and decreased protein C and fibrinogen in animal plasma, which all improved following infusion of rhAPC." (PMID 18702832, 2008). "In endotoxemia, the neutropenic rats had lower plasma TNF-α (116 ± 73 vs. 202 ± 31 pg/ml) and higher plasma MIP-2 (26.8 + 11.9 vs. 15.6 + 6.9 ng/ml) when compared to non-neutropenic rats." (PMID 17397554, 2007). "Tumor necrosis factor-α plays an important role in initiating acute lung injury after endotoxemia in the normal host." (PMID 17397554, 2007). "In this model of endotoxemia, the TNF-α concentration was markedly decreased while MIP-2 was elevated in the plasma of the neutropenic, endotoxemic compared to non-neutropenic, endotoxemic rats." (PMID 17397554, 2007). "Patients with lean MASLD have endotoxemia, and LPS stimulates macrophages to release inflammatory factors such as tumor necrosis factor α (TNF-α) and interferon-γ by binding with Toll-like receptors (TLR), thus damaging the metabolic adaptability of the human body." (PMID 40239896, 2025). "The restoration of intestinal barrier function decreases intestinal permeability, which reduces the concentration of LPS entering the circulation, and reduced endotoxemia leads to decreased serum concentrations of inflammatory cytokines such as TNF-α and IL-6, thereby attenuating CLGI." (PMID 39201665, 2024). "When comparing ATB+DSS with P. aeruginosa (ATB+DSS+PA) and ATB+DSS mice, P. aeruginosa exacerbated loose stool in almost all mice, leaky gut parameters (bacteremia, FITC-dextran, and endotoxemia), systemic inflammation (TNF-α, IL-6, and IL-10), and liver damage (alanine transaminase)." (PMID 39546435, 2024). "Furthermore, JQ1 has been found to reduce levels of IL-6 and TNF and prevent death in mice induced with LPS-induced endotoxemia." (PMID 38407669, 2024). "The results of our research showed that the administration of MLT to animals with endotoxemia led to a decrease in the level of cytokines TNF-α and IL-6 in the liver tissue compared to the group of animals administered LPS, in which their concentration was significantly increased." (PMID 38203627, 2023). "Cholinergic anti-inflammatory pathways are potently activated by electrical VNS, as demonstrated in previous studies that prevented the release of pro-inflammatory cytokines such as TNF-⍺, IL-1β, IL-6, and IL-18 during endotoxemia, and in patients receiving tragus stimulus following acute MI." (PMID 37801130, 2023). "Moreover, IID activates downstream proinflammatory factors such as IL-6 and TNF-α, which are mainly regulated by NFκB-activated endotoxemia by upregulating the levels of IL-6 and TNF-α, inducing intestinal mucosal injury and chronic inflammatory bowel disease." (PMID 37529040, 2023). "These early kinetics of SUMO1 at 100 and 150KDa mimic serum TNFα levels during endotoxemia." (PMID 37520526, 2023).